CASP4 (caspase 4)
Diseases named in the same sentence as CASP4 in open-access papers (continued):
Sharing a sentence is not in itself a finding about the gene and the disease.
periodontitis (7 papers, 2020 to 2025). An acute or chronic inflammatory process that affects the tissues that surround and support the teeth. "In a rat model of periodontitis, drug inhibition of Caspase-4 or IL-1β antibody significantly reduced alveolar bone loss and periodontal soft tissue injury." (PMID 38191432, 2024). "Pharmacological inhibition of caspase-4 or IL-1β antibody blockade in a rat periodontitis model lead to the significantly reduced loss of alveolar bone and periodontal ligament damage." (PMID 33869229, 2021). "Clinical and experimental evidence strongly support the involvement of caspase-1 and caspase-4 in the pathogenesis of periodontitis." (PMID 40137780, 2025). "Future studies exploring the therapeutic potential of caspase-4 inhibition in animal models of AD and periodontitis will be valuable in advancing our understanding of its role in chronic inflammation and neurodegeneration associated with AD and ADRD." (PMID 40497980, 2025). "CASP4/GSDMD triggered by bacterial LPS leads to focal death of periodontal ligament stem cells in periodontitis patients." (PMID 38800469, 2024). "Similar to human periodontal tissues, Gsdmd cleavage, mature IL-1β release and caspase-4 activation were both significantly increased in ligature-induced rat periodontitis." (PMID 33869229, 2021). "A periodontitis rat model was generated by ligatures around the first maxillary molar and then treated with caspase-4 specific inhibitor (Z-LEVD-FMK) or IL-1β antibody for 14 days." (PMID 33869229, 2021). "Collectively, either inhibiting the activation of caspase-4 or blocking the function of IL-1β can attenuate periodontitis-mediated tissue damage, which indicates the critical role of caspase-4-mediated non-canonical pyroptosis in rat periodontitis." (PMID 33869229, 2021). "The staining for Caspase-4 was obviously stronger in both epithelium and lamina propria of periodontits group, suggesting that Caspase-4 also participated in the mechanism of periodontitis." (PMID 32903638, 2020). "In order to observe the expression of Caspase-4 in periodontitis tissue more intuitively, we performed IHC for Caspase-4 staining in human gingival tissues." (PMID 32903638, 2020). "Understanding the specific contributions of caspase-1 and caspase-4 in periodontitis pathogenesis could pave the way for novel therapeutic interventions aimed at restoring immune homeostasis and preventing disease progression." (PMID 40137780, 2025). "In this work, we also confirmed that the activation of caspase-4/11 was elevated in human periodontitis samples and in murine periodontitis models and that P. gingivalis (a gram-negative periodontopathogen) induced PDLSC pyroptosis with the cleavage of GSDMD and IL-1β release." (PMID 33869229, 2021). "Furthermore, macrophages obtained from periodontitis patients were stimulated with E. coli LPS and P. gingivalis LPS while the expression of caspase-4 and IL-1β was seen for the cells stimulated with E. coli LPS." (PMID 35008798, 2021). "Caspase-4 was also highly expressed in the periodontal tissues of periodontitis patients." (PMID 33869229, 2021). "The induction of GSDMD in human periodontitis and ligature-induced rat periodontitis and the restorative effect of IL-1β antibody and caspase-4 inhibitor in rat periodontitis led us to hypothesize that GSDMD-driven pyroptosis was probably the key determinant of periodontitis." (PMID 33869229, 2021). "To extend our in vitro findings, we next investigated the role of caspase-4-mediated non-canonical pyroptosis in ligature-induced rat periodontitis." (PMID 33869229, 2021). "Moreover, Z-LEVD-FMK, a caspase-4 specific inhibitor, led to inhibition of GSDMD cleavage, caspase-4 activation, and IL-1β release in a periodontitis rat model." (PMID 35008798, 2021). "Mechanistic investigation revealed that the caspase-4/GSDMD/IL-1β non-canonical pyroptosis pathway was the major contributor to the pathogenesis of periodontitis." (PMID 33869229, 2021).
colorectal cancer (6 papers, 2020 to 2023). A primary or metastatic malignant neoplasm that affects the colon or rectum. "Caspase-4 can be cleaved by NF-κB to participate in pyroptosis, which is considered a unique form of cell death in colorectal cancer cells." (PMID 37211606, 2023). "Secretoglobin 3A2-lipopolysaccharide (LPS) can eliminate human colorectal cancer cells by regulating the mechanism of CASP4-related pyroptosis." (PMID 35938142, 2022). "Moreover, EPEC infection of the colorectal cancer cell line Caco-2 triggers caspase-4–dependent release of IL-18, suggesting that EPEC may also induce pyroptosis in IECs." (PMID 33378358, 2020). "Therefore, we proposethat IL-17A activates the NF-κB pathway, triggering the activation of caspase-4 and the cleavage of GSDMD in colorectal cancer cells." (PMID 37211606, 2023).
esophageal squamous cell carcinoma (6 papers, 2020 to 2022). Esophageal squamous cell carcinoma (ESCC) is a type of esophageal carcinoma (EC) that can affect any part of the esophagus, but is usually located in the upper or middle third. "In esophageal squamous cell carcinoma, CASP4 served as a prognostic biomarker and is associated with poor prognosis." (PMID 35692583, 2022). "As the tumor-suppressor gene, CASP4 is associated with the poor outcome of esophageal squamous cell carcinoma." (PMID 34938319, 2021). "For example, CASP4 upregulation is related to better OS in esophageal squamous cell carcinoma (ESCC) and GC, whereas in RCCC and NSCLC upregulation is associated with poor prognoses." (PMID 36552744, 2022).
psoriasis (6 papers, 2019 to 2025). An autoimmune condition characterized by red, well-delineated plaques with silvery scales that are usually on the extensor surfaces and scalp. "Western blot analysis showed that psoriasis-derived MDMs had elevated expression of pyroptosis-related proteins, Caspase 1 and Caspase 4, when compared to healthy controls." (PMID 40722833, 2025). "In vitro experiments confirmed that MDMs derived from psoriasis patients overexpressed pyroptosis-related molecules (Caspase 1 and Caspase 4) as well as pro-inflammatory cytokines (TNFα, IL6, IL1β) when compared to healthy controls." (PMID 40722833, 2025). "We found that the interaction of CASP10 - CASP1, CASP10- CASP3, CASP10- CASP4, CASP10- CASP9, CASP10- CASP12, CASP8 - CASP3, CASP8 - CASP4, and CASP1 - CASP12 is important for the risk of psoriasis." (PMID 30906769, 2019). "Interestingly, compared with psoriasis skin-derived S.C cells, control skin cells highly expressed pyroptosis-related genes (CASP4, GSDMA, and GSDMC), suggesting that psoriasis skin-derived S.C cells were not sensitive to pyroptosis." (PMID 35962439, 2022). "The non-classical pathway of pyroptosis mediated by caspase-4 and caspase-5 was identified as kernel regulators in psoriasis by a random forest algorithm in the current study." (PMID 36110207, 2022). "Notably, genes such as Nlrp3, Casp1, Casp4, IL-1β, IL-18, and Stat1 had high degree values, indicative of their significant position in the PPI network and potential targets for FZHFZY treatment of psoriasis." (PMID 41383588, 2025).
viral infection (5 papers, 2009 to 2025). "A greater number of genes are upregulated in DCs after MRV infection, many of which are involved in the innate immune response (i.e. Ifit1, Ifit3, Mx1, Gbp2, Oasl1, Isg15, Ccr1, Ifitm2, Oaxl2, Casp1, Casp4) that would be predicted in response to a viral infection." (PMID 38895117, 2024). "DEGs unique to infected cells mapped to host defense (MYD88, C3, CASP4, JAK2, and OSM), viral infection (RNASE6 and SVVORFs), and protein synthesis (RPL18 and RPS16)." (PMID 38887303, 2024).
clear cell renal cell carcinoma (4 papers, 2020 to 2022). "Abnormal expression of CASP4 in clear cell renal cell carcinomas has been reported as an important prognostic factor affecting prognosis." (PMID 34485134, 2021). "The dysregulation of caspase 4 (CASP4) expression is related to the occurrence, development, and outcome of many malignant tumors; however, its role in clear cell renal cell carcinoma (ccRCC) remains unclear." (PMID 33584797, 2020).
gastric cancer (4 papers, 2014 to 2023). A primary or metastatic malignant neoplasm involving the stomach. "G503 induces apoptosis in SGC7901 gastric cancer cells primarily through the mitochondrial apoptotic pathway and partly through the activation of caspase-4 in the endoplasmic reticulum." (PMID 25268882, 2014). "Additionally, CASP4 triggers pyroptosis by cleaving gasdermin D51 and may act as a tumor suppressor in gastric cancer and esophageal squamous cell carcinoma." (PMID 37144561, 2023).
lupus (4 papers, 2021 to 2024). "We then focused on GSDMD, which was significantly upregulated together with caspase-1 and caspase-4 (also known as caspase-11 in mice) upregulation in lupus mice." (PMID 36797275, 2023).
idiopathic pulmonary fibrosis (3 papers, 2019 to 2024). Idiopathic pulmonary fibrosis (IPF) is a nonneoplastic pulmonary disease that is characterized by the formation of scar tissue within the lungs in the absence of any known cause. "Similarly, in our previous work, we found that IL-1α was responsible for TGF-β release from idiopathic pulmonary fibrosis (IPF)-derived PBMCs in a caspase-4-, but not caspase-1-, dependent manner." (PMID 30930781, 2019).
leukemia (3 papers, 2013 to 2022). A malignant (clonal) hematologic disorder, involving hematopoietic stem cells and characterized by the presence of primitive or atypical myeloid or lymphoid cells in the bone marrow and the blood. "As an exception, some leukemia cells that are resistant to SSa treatment had high caspase-4 expression." (PMID 29245990, 2017). "Natural agents, such as curcumin from the turmeric (Curcuma longa) have been reported to induce pro-apoptotic ER stress in human leukemia HL-60 cells by upregulating the expression of phosphorylated PERK, CHOP, Bip and cleaved caspase-4." (PMID 24367485, 2013).
lung adenocarcinoma (3 papers, 2020 to 2024). A carcinoma that arises from the lung and is characterized by the presence of malignant glandular epithelial cells. "We observe that elevated CASP4 expression in the primary tumor is associated with cancer progression in patients with lung adenocarcinoma." (PMID 38849594, 2024). "CASP4 enhances the expression of genes associated with angiogenesis and cell migration in lung adenocarcinoma cell lines through nuclear factor kappa-light chain-enhancer of activated B cell signaling without stimulation by lipopolysaccharide or tumor necrosis factor." (PMID 38849594, 2024). "Most notably, lung adenocarcinoma cells with high CASP4 expression are more prone to IFN-γ-induced pyroptosis than those with low CASP4 expression." (PMID 38849594, 2024). "Here, we report that CASP4 in lung adenocarcinoma cells contributes to both tumor progression via angiogenesis and tumor hyperkinesis and tumor cell killing in response to high interferon (IFN)-γ levels." (PMID 38849594, 2024). "Our findings indicate that the CASP4 level in primary lung adenocarcinoma can predict metastasis and responsiveness to high-dose IFN-γ therapy due to cancer cell pyroptosis." (PMID 38849594, 2024). "Further, among all lung adenocarcinoma patients analyzed, three patients expressed high levels (upper 20%) of all three critical genes SCGB3A2, SDC1, and CASP4, and all of them survived up to 40 months, although the “n” number is too small to establish significance." (PMID 33452234, 2021).
osteoarthritis (3 papers, 2019 to 2024). A noninflammatory degenerative joint disease occurring chiefly in older persons, characterized by degeneration of the articular cartilage, hypertrophy of bone at the margins and changes in the synovial membrane. "Alteration of the osteoarthritis pathway due to RARγ agonist treatment was associated with the up-regulation of catabolic genes (ADAMTS5, HES1, and MMP13), inhibition of cartilage matrix anabolic genes (COL2A1, ACAN, and SOX9) and the up-regulation of death genes (CASP4)." (PMID 32294904, 2020). "The changes in expression of the DEGs listed in the osteoarthritis pathway included strong down-regulation of cartilage matrix molecules (COL2A1, MATN3, and ACAN) and up-regulation of matrix proteases (ADAMTS5 and MMP13) and apoptosis-related molecules (CASP4)." (PMID 32294904, 2020).
ulcerative colitis (3 papers, 2021 to 2025). An inflammatory bowel disease involving the mucosal surface of the large intestine and rectum. "Consistent with the inflammatory role of caspase-4, previous data have shown that stromal caspase-4 expression is associated with infiltrating macrophage, neutrophil, and lymphocyte cells, which correlates with the degree of inflammation in ulcerative colitis patient tissues." (PMID 39866724, 2025). "In patients with ulcerative colitis, the level of GPx8 in the macrophages of their colon tissue was reduced, and the level of caspase-4/11 was increased." (PMID 35208621, 2022). "Pyroptosis, a highly inflammatory form of lytic programmed cell death, with initiation via activation of caspase family, including caspase-1, caspase-4, caspase-5, and caspase-11, can be triggered by various diseases, such as ulcerative colitis." (PMID 35008842, 2021).
urinary tract infection (3 papers, 2019 to 2023). "The inflammasome-associated proteins caspase-1, caspase-4 and NLRP3 have been emphasised to be essential in the host cell response during urinary tract infection (UTI) by regulating IL-1β release." (PMID 35132157, 2022). "The inflammasome-associated proteins caspase-1, caspase-4 and NLRP3 have been emphasised to be vital in the host response during urinary tract infection by regulating IL-1β release." (PMID 35132157, 2022).
acute kidney injury (2 papers, 2021 to 2024). Sudden and sustained deterioration of the kidney function characterized by decreased glomerular filtration rate, increased serum creatinine or oliguria. "During acute kidney injury (AKI) and renal fibrosis induced by nondiabetic renal disease, the mechanism of pyroptosis involves classical pyroptosis in the caspase-1/GSDMD pathway as well as nonclassical pyroptosis in the caspase-4/5/11 pathway." (PMID 39000237, 2024).
breast tumor (2 papers, 2020 to 2021). "Zhu and colleagues confirmed that TET2 inhibited the carcinogensis and progression of breast tumors by regulating caspase-4." (PMID 32014008, 2020).
Burkholderia Infections (2 papers, 2021). Infections with bacteria of the genus BURKHOLDERIA. "In agreement with this, we show that in human epithelial cells, IFNs and caspase-4-dependent pyroptosis provide protection against Burkholderia infection, whereas pyroptosis in primary hMDMs is driven by IFN-dependent and -independent mechanisms." (PMID 34399626, 2021). "It is possible that Burkholderia infection triggers stress that activates NLRP1 inflammasome activation, leading to ASC and CASP1 activation, although the participation of other inflammasomes such as the non-canonical caspase-4 could not be ruled out." (PMID 34821529, 2021).
cognitive deficits (2 papers, 2017 to 2021). "We did not determine whether other caspases are activated downstream of Casp6 in our mouse model and it remains a possibility that the inhibition of other caspases such as Casp4, 8, 9, and 10 additionally contributed to the improvement of cognitive deficits mediated by the over-expression of Casp6." (PMID 28241839, 2017).
dementia (2 papers, 2024 to 2025). Loss of intellectual abilities interfering with an individual's social and occupational functions. "This DNA demethylation program was coupled with increased transcript and protein expression levels of CASP4 in human AD samples compared to non-dementia controls." (PMID 38326859, 2024). "Our work identified that CASP4 (CASP11) is upregulated in the temporal lobe (Brodmann area 38) of AD patients compared to age- and sex-matched non-dementia controls." (PMID 38326859, 2024).
glioblastoma (2 papers, 2015 to 2020). The most malignant astrocytic tumor (WHO grade IV). "To further characterize gene expression in the Ad-GSCs and Sp-GSCs tumor xenografts, we examined the expression of genes previously defined to be characteristic of the Classical (FGFR3, PDFA, EGFR, AKT-2 and Nestin) and Mesenchymal (CHI3L1, TRADD, NF1, RelB and CASP4) glioblastoma subtypes." (PMID 25955030, 2015).
Hypertension (2 papers, 2020 to 2023). The presence of chronic increased pressure in the systemic arterial system. "When metabolic comorbidities were analyzed (hypertension, T2DM, and DLP), their improvement was associated with increased baseline levels of the inflammasome activation component IL18R (CASP4 and TGFB tended to be also overexpressed in these patients)." (PMID 37867510, 2023).
infantile neuronal ceroid lipofuscinosis (2 papers, 2009 to 2011). A form of neuronal ceroid lipofuscinosis (NCL) characterized by onset during the second half of the first year of life and rapid mental and motor deterioration leading to loss of all psychomotor abilities. "Further, caspase-4 is present in neurons and neuronal stress can activate this caspase and mediate apoptosis, e.g. in INCL (infantile neuronal ceroid lipofuscinosis) and probably in AD." (PMID 20035627, 2009).
inflammatory bowel disease (2 papers, 2020 to 2025). A spectrum of small and large bowel inflammatory diseases of unknown etiology. "Here, we profile caspase-4 expression across 2 distinct CRC development pathways, sporadic CRC (sCRC) and inflammatory bowel disease-associated CRC (IBD-CRC), to examine its utility as a novel biomarker for CRC risk and diagnosis." (PMID 39866724, 2025).
inflammatory liver diseases (2 papers, 2021 to 2022). "Taken together, these data demonstrate an association of hepatic caspase-4 expression with severity of liver disease in cirrhosis, and a further association with disease trajectory in hospitalized patients with decompensated cirrhosis." (PMID 34336828, 2021). "Moreover, the roles of caspase-4/5 non-canonical inflammasomes in human patients with inflammatory liver diseases have not yet been investigated." (PMID 35563377, 2022). "Therefore, further studies investigating the roles of the caspase-4/5/11 non-canonical inflammasome in various inflammatory liver diseases in appropriate animal models and human patients and the underlying mechanisms are required." (PMID 35563377, 2022).
influenza (2 papers, 2022 to 2025). An acute viral infection of the respiratory tract, occurring in isolated cases, in epidemics, or in pandemics; it is caused by serologically different strains of viruses (influenzaviruses) designated A, B, and C, has a 3-day incubation period, and usually lasts for 3 to 10 days. "In contrast, full-length and fully cleaved caspase-4, as well as full-length and cleaved GSDMD, were readily detected in BAL fluid from macaques with severe influenza." (PMID 35271686, 2022). "In contrast, the role of the non-canonical caspase-4/5 pathway in influenza pathogenesis remains largely unexplored, presenting an important area for future investigation." (PMID 41305513, 2025). "In contrast, genes associated with pyroptosis, including CASP4, NLRP3 and GSDMD, were highly expressed in whole lung lysates from macaques with lethal influenza but not from uninfected animals." (PMID 35271686, 2022).
parasitic infection (2 papers, 2022). "However, caspase-4 as the human ortholog of caspase-11 was less characterized, especially in the context of parasitic infections." (PMID 35303042, 2022).